TILRLS (TCL1A interacting lncRNA, retroperitoneal liposarcoma associated)
Synonyms: PILRLS
Gene: Long non-coding RNA gene on chromosome 5 (67,268,022 to 67,270,182, forward strand). Ensembl gene ENSG00000251206.
Diseases named in the same sentence as TILRLS in open-access papers:
TILRLS is named in the same sentence as 3 diseases in open-access papers, as found by Europe PMC text mining. Sharing a sentence is not in itself a finding about the gene and the disease.
TILRLS shares sentences with these, for which no sentence is quoted: cancer (1 paper); liposarcoma (1); tumor (1).